ABCG1 (ATP binding cassette subfamily G member 1)
Diseases named in the same sentence as ABCG1 in open-access papers (continued):
Sharing a sentence is not in itself a finding about the gene and the disease.
metabolic syndrome (24 papers, 2015 to 2025). A cluster of metabolic risk factors for CARDIOVASCULAR DISEASES and TYPE 2 DIABETES MELLITUS. "It is well-known that ABCA1/ABCG1 plays a central role in reverse cholesterol transport (RCT); the dysfunction of ABCA1/ABCG1 caused by the rs2910164 polymorphism may therefore result in dyslipidemia." (PMID 34646311, 2021). "These constellations of findings suggest that ABCG1 may play a role in predisposing to or mediating the effects of the metabolic syndrome." (PMID 34183656, 2021). "Metabolic syndrome was consistently associated with increased methylation in the ABCG1 gene in the discovery and replication datasets, a gene that encodes a protein in the ATP-binding cassette transporter family and is involved in intra- and extra-cellular signaling and lipid transport." (PMID 29643945, 2018). "The presence of metabolic syndrome further impaired ABCG1-mediated CEC in Group M. Group M had higher plasma-induced CLC than Group G and controls (p < 0.001)." (PMID 33352841, 2020). "This study was aimed at evaluating and comparing ABCA1 and ABCG1 genes expression in metabolic syndrome patients and healthy individuals." (PMID 26788366, 2015). "The obtained results indicated a significant decrease in ABCG1 expression in metabolic syndrome patients compared with healthy individuals." (PMID 26788366, 2015). "Additionally, ABCG1 expression in metabolic syndrome patients has been shown to be significantly lower." (PMID 36557031, 2022). "Together, these findings suggest that ABCG1 expression plays a key role in metabolic syndrome, and that DNA methylation may be substantially involved in this pathway." (PMID 28264653, 2017). "However, the connection between ABCG1 and T2D/related traits as well as dyslipidemia is further supported by animal and human studies." (PMID 27019061, 2016). "Decrease in ABCG1 expression in metabolic syndrome patients compared to healthy individuals suggests that hyperglycemia, related metabolites, and hyperlipidemia over the transporter capacity resulted in decreased expression of ABCG1." (PMID 26788366, 2015). "Differences in mean DNA methylation (%) of (A) cg06500161 in ABCG1 and of (B) cg06638433 in IGF2BP1 gene by metabolic syndrome and components." (PMID 29643945, 2018).
breast carcinoma (19 papers, 2013 to 2025). "Similar to ABCA1, ABCG1 also plays a crucial role in tumorigenesis in lung cancer and breast cancer." (PMID 39349433, 2024). "Meanwhile a significant change in the expression of ABCG1 gene was declared upon DMBA-induced breast cancer in rats recording 0.76-fold change as compared with healthy rats." (PMID 38827789, 2024). "It has been reported that activation of LXR deprives MCF-7 breast cancer cell membranes of cholesterol essential for their growth by stimulating its efflux via ABCG1, resulting in inhibition of cell proliferation and induction of apoptosis." (PMID 31477154, 2019). "A significant correlation between ABCG1 expression and poor prognosis in a breast cancer cohort study was found with an endpoint of distant metastasis-free survival with a minimum P-value 0.00097." (PMID 30364132, 2018). "The expression of ABCG1 is increased in breast cancer patients during neoadjuvant therapy with 5-fluorouracil-doxorubicin-cyclophosphamide, and increased levels of ABCG1 predict poor prognosis." (PMID 27029062, 2016). "This study investigated ABCA1 and ABCG1 in connection to breast cancer chemoresistance." (PMID 38827789, 2024). "LXR activation may deprive breast cancer cells of cholesterol by stimulating its efflux through the expression of ABCG1 (ATP-binding cassette sub-family G member 1), a cell carrier of cholesterol." (PMID 33374116, 2020). "Thus, ABCG1 may be involved in breast cancer through the regulation of cholesterol transport, but this role requires new research." (PMID 39857239, 2024). "Thus, ABCG1-dependent cholesterol efflux results in an antiproliferative effect on breast cancer." (PMID 39857239, 2024). "In these dysfunctional ORGs, combined with relevant researches, ABCG1 is a potential target for treating ovarian cancer associated with ECM1-activated signaling, while LEPR is the one of breast cancer risk factors, indicating ORGs might play important roles in PRAD." (PMID 37788005, 2023). "Deep deletions were significantly more prevalent in prostate cancer than in breast cancer, with frequent occurrences in ABCG2, ABCG1, ABCC4, ABCA2, ABCC2, ABCC7/CFTR, and ABCC9." (PMID 40641097, 2025). "In addition, ABCG1 may play a role in breast cancer due to its role in cholesterol transport." (PMID 39857239, 2024). "miR-128-2, a pro-apoptotic miRNA was shown to inhibit ABCA1, ABCG1 and RXRα mRNA and protein expression in cell lines such as MCF-7 breast cancer and HepG2 liver hepatocellular carcinoma." (PMID 32577155, 2020). "Of all the ligand-responsive genes, 83 (23 upregulated and 60 downregulated) were responsive in all four breast cancer cell lines, including known LXR target genes such as ABCA1 and ABCG1, and they represent candidate mechanisms for the anti-proliferative effects of LXR ligands in these cell lines." (PMID 23809258, 2013). "To determine whether the increase in ABCG1 and ABCA1 expression induced by 4-cholesten-3-one was LXR-dependent, we decided to suppress LXR activity in breast cancer cells using an SR9238 inverse agonist and to subsequently study the mRNA expression of LXR target genes, ABC transporters." (PMID 31477154, 2019).
coronary heart disease (17 papers, 2013 to 2025). "Two population-based cohorts on 2306 individuals indicated that higher methylation at cg27243685 site of ABCG1 gene increased the serum TG level and was associated with an increased risk of coronary heart disease." (PMID 35551677, 2022). "Genetically the association of ABCG1 with coronary artery disease have been mixed." (PMID 39088185, 2024). "Thus, Ser630Leu, a mutation leading to an amino acid substitution in ABCG1, increases the risk of developing a myocardial infarction by seven times and coronary heart disease by six times." (PMID 34940525, 2021). "A protective role for ABCG1 in coronary artery disease has been observed in the Copenhagen City Heart Study with three variants found to be associated with myocardial infarction." (PMID 39088185, 2024). "It has also been shown that a variation in the coding region of the ABCG1 gene resulting in an amino acid substitution in ABCG1 (Ser630Leu) significantly increases the risks of myocardial infarction and coronary heart disease in general." (PMID 39857239, 2024). "For example, the differential methylation of ABCG1 has been associated with HDL and triglyceride (TG) levels in coronary heart disease." (PMID 39766777, 2024). "Methylation of ATP binding cassette subfamily G member 1 (ABCG1) and ATP binding cassette subfamily A member 1 (ABCA1) has been associated with coronary heart disease." (PMID 36032780, 2022). "Moreover, serum levels of miR-27a were found to be inversely related to two cholesterol transporters: ABCA1 and ABCG1 gene expression in coronary heart disease patients." (PMID 37628623, 2023). "Finally, a large-scale clinical study has revealed that mutations in the SP1 binding site of the promoter in ABCG1 reduced SP1 binding and increased risk of myocardial infarction and ischemic heart disease." (PMID 28666417, 2017). "Analysis of the relationship between ABCG1 promoter methylation and coronary heart disease (CHD) was investigated in a small group of 85 CHD patients and 54 participants without CHD in the Han Chinese population." (PMID 28869506, 2017).
Hypercholesterolemia (15 papers, 2017 to 2025). An increased concentration of cholesterol in the blood. "Another study on patients with familial hypercholesterolemia found significant association between ABCG1 DNA methylation and HDL-C, LDL-C and TG levels only in women." (PMID 35551677, 2022). "Involvement of ABCG1 in maternal-to-fetal cholesterol transport was confirmed in a recent study on maternal supraphysiological hypercholesterolemia, and its decreased expression was associated with decreased efflux." (PMID 34829614, 2021). "The clearest evidence for a role of excessive myelopoiesis in neutrophilia and monocytosis comes from studies of animal models with hypercholesterolemia and genetic deficiency in genes involved in cholesterol efflux from hematopoietic cells such as Abca1−/−/Abcg1−/− or Apoe−/− mice." (PMID 32086626, 2020). "The mRNA expression of ABCG1, the membrane transporter that mediates cellular efflux of cholesterol, was significantly induced by maternal hypercholesterolemia." (PMID 28199412, 2017). "Collectively, these findings show that in the setting of hypercholesterolemia, SMC-Abca1/Abcg1 deficiency induces bladder wall SMC lipid accumulation, bladder wall thinning, loss of SMC markers, and an increase in Lgals3+ SMCs, macrophage-like, and fibroblast-like cells." (PMID 39931819, 2025). "Moreover, unlike the situation reported with ABCG1-myeloid deficiency where the tumor protective effect was observed under conditions of hypercholesterolemia, this does not appear to be a prerequisite to elicit tumor protection with ABCA1-myeloid deficiency." (PMID 29069761, 2017). "Measurement of blood DNA methylation in Canadian Familial Hypercholesterolemia patients did not allow to establish any association between methylation levels at a single ABCG1 CpG site (CpGC3) and a prior history of CAD in a small subset of individuals (Non-CAD (n = 22) vs CAD (n = 22))." (PMID 28869506, 2017). "In our study, hypermethylation of promoters of key genes regulating cholesterol metabolism such as PCSK9, LRP1, ABCG1, ANGPTL4, SREBF1 and NR1H2, were found in obese patients with hypercholesterolemia." (PMID 33028190, 2020).
lung carcinoma (15 papers, 2019 to 2025). "The expression of ABCG1 is significantly upregulated in variant cancers including metastatic colon cancer, cholangiocarcinoma, glioma, lung cancer, and ovarian cancer." (PMID 38896016, 2024). "The methylation levels of three CpGs (located at LMNA, SREBF1, and ABCG1) in whole blood were inversely associated with lung cancer risk." (PMID 33939316, 2021). "Additionally, studies have shown that ABCG1 regulates markers associated with apoptosis, proliferation, migration, and invasion of lung cancer cells." (PMID 40508156, 2025). "The upregulation of ABCG1 in lung cancer is associated with increased cancer cell proliferation, migration, and invasion, while inhibition by betulinic acid leads to G1 phase arrest, decreased proliferation, and migration potential of lung cancer cells." (PMID 39308527, 2024). "The cg11024682 and cg06500161 annotated to SREBF1 and ABCG1 genes, could mediate the associations of BMI and lung cancer risk." (PMID 33939316, 2021). "In this study, we found that cg11024682 (in SREBF1) and cg06500161 (in ABCG1) could mediate 45.3% and 19.5% of the association between BMI and decreased lung cancer risk, respectively." (PMID 33939316, 2021). "ABCG1 promotes cell proliferation, migration, and invasion in lung cancer cells, and is associated with expression of anti-apoptotic proteins (B-cell lymphoma 2 (BCL2) or Myeloid-cell leukemia 1 (MCL1), stemness markers (CD133 and ALDH), and proliferative markers (such as c-Myc)." (PMID 34820325, 2021). "Although ABCG1 exhibits an anti‐tumor effects from some tumors through excessive cholesterol efflux, the outcomes of clinical lung cancer patients treated with cholesterol depletion strategy are still dismal." (PMID 38896016, 2024). "ABCG1 promoted proliferation of HKULC4 lung cancer cells by regulating their proliferation, apoptosis, and cancer stem cell-associated markers." (PMID 34281263, 2021). "Another team showed lung cancer inhibition by betulinic acid nanoparticles via ABCG1 downregulation in HKULC2 cells." (PMID 34281263, 2021). "High expression of ABCG1 has been observed in pancreatic cancer, breast cancer, lung cancer, and colon cancer." (PMID 34820325, 2021). "ABCG1 was found to be a potential biomarker for lung cancer, head and neck squamous cell carcinoma, and prostate cancer." (PMID 33825659, 2021). "We isolated Sca-1+Abcg1+cells from Gprc5a-KO mice and SPA+ABCG1+ cells from tumor samples from patients with lung cancer, respectively and injected these cells into NOD/SCID mice via the tail vein to evaluate the tumor initiation capacity of this subset." (PMID 32157214, 2020). "These capacities of SPA+ (surfactant protein A) ABCG1+ cells were verified in samples from patients with lung cancer." (PMID 32157214, 2020). "The observed downregulation of ABCG1 in our model contrasts with these findings in lung cancer." (PMID 40508156, 2025). "Moreover, it seems to be upregulated in lung cancer tissue, and aberrant expression of ABCG1 in lung cancer cells promotes proliferation, migration, and tumor invasion." (PMID 37108308, 2023). "ABCG1 has been shown to be a potential oncogene for lung cancer." (PMID 33939316, 2021). "Thus, the present study identified Sca-1+Abcg1+ cells as a population of LCICs and provided applicable markers for the early diagnosis of lung cancer." (PMID 32157214, 2020). "Thus, ABCG1 may function as a modulator of proliferation, migration, invasion, apoptosis, and miRNA regulation in lung cancer cells." (PMID 39857239, 2024). "AT2 cells with ABCG1 expression could be one of the originating cell populations of lung cancer." (PMID 32157214, 2020). "In addition, we also found the GPRC5A is down-regulated in lung tissues of pneumonia, suggesting the GPRC5A deficiency might promote the enrichment of SPA+ABCG1+ subset in S/TB region and SPA+ABCG1+might serve as markers for the early diagnosis of lung cancer." (PMID 32157214, 2020).
lung carcinoma (continued). "ABCG1 overexpression promotes tumor cell proliferation and enhances the expression of anti-apoptotic proteins BCL2 and MCL1 in HKULC4 lung cancer cells." (PMID 39857239, 2024). "More importantly, cg11024682 in SREBF1 and cg06500161 in the ABCG1 gene could mediate 45.3% and 19.5% of the BMI‐NSCLC association, respectively, suggesting the biological role of DNA methylation on the association between BMI and reduced lung cancer risk in the Chinese populations." (PMID 33939316, 2021). "Although which of ABC transporters plays the key function remains unclear, ABCG1 is still a potential research subject, because it attenuates cholesterol levels in TAM‐like macrophages to induce tumor‐promoting actions in human lung cancer cells." (PMID 38896016, 2024). "In contrast to studies in lung cancer and normal haemopoietic stem cells, decreased ABCG1 had no direct effect on the proliferation or apoptosis of ES cells." (PMID 36765727, 2023). "Betulinic acid NPs on lung cancer cells (HKULC2, H1299, and H23) inhibited proliferation and metastatic ability and arrested the cell cycle through the downregulation of ATP-binding cassette and transporter G1 (ABCG1) oncogene expression." (PMID 37538179, 2023). "Interestingly, after tumor formation, an enrichment of the Sca-1+Abcg1+ or SPA+ABCG1+ subset in the SB and tumor region was also observed, indicating that this subset is one of the initiation cells of lung cancer." (PMID 32157214, 2020). "In lung cancer, the progenitor AT2 cells express high ABCG1 levels through the NF‐kB/ECM1/α6β4 axis to confer self‐renew and tumor initiation capacities, suggesting ABCG1 may be a potential biomarker for early diagnosis." (PMID 38896016, 2024). "We found that the Sca-1+Abcg1+cells from Gprc5a-KO mice and SPA+ABCG1+ cells of tumor samples from patients with lung cancer both could develop tumors in the lungs, while the Sca-1+Abcg1− and SPA+ABCG1− subsets (not P5 subset) failed to initiate tumor formation." (PMID 32157214, 2020).
Insulin resistance (11 papers, 2017 to 2025). Increased resistance towards insulin, that is, diminished effectiveness of insulin in reducing blood glucose levels. "ABCG1 is also related to insulin resistance, and the association of a related CpG site cg06500161 identified by DMP analysis with diabetic markers has been reported." (PMID 38137029, 2023). "For instance, TXNIP, which includes cg19693031 (chosen in 43 DNAm-metabolomics models), was previously associated to hyperglycaemia and insulin resistance, and ABCG1, nearby cg06500161 (in 42 DNAm-metabolomics models) was associated to plasma lipid levels and stroke." (PMID 39154540, 2024). "Another study found that differentially methylated CpG sites at well-established lipid-associated genes ABCG1 and SREBF1 were also associated with insulin resistance and BMI in blood, liver, and adipose tissues." (PMID 40176173, 2025). "These markers located in ABCG1, PHOSPHO1, SOCS3, SREBF1, and TXNIP were associated with metabolic measures of insulin resistance including glucose concentration, BMI, waist-to-hip ratio, and homeostatic model assessment for insulin resistance (HOMA-IR)." (PMID 32211026, 2020). "The model proposed based on our data from statin-induced insulin resistance is that hypomethylation of the HDAC9 promoter is correlated with HDAC9 gene expression, which acts as a transcriptional repressor to ABCG1 expression and thereby adipocyte differentiation and metabolic dysfunction." (PMID 32410704, 2020). "Thus, decreased expression of ABCG1, ABCA1, and ACSL3 could impair insulin secretion and lead to insulin resistance." (PMID 32612641, 2020).
Hyperglycemia (10 papers, 2011 to 2025). An increased concentration of glucose in the blood. "Accumulating experimental evidence suggest that ABCA1 or ABCG1 expression in macrophages is suppressed by high-glucose concentrations in vitro and by hyperglycemia ex vivo." (PMID 28408925, 2017). "Fourth, UDCA reduced foam cell formation via upregulation of ABCA1 and ABCG1 expression, reduction of hyperglycemia-induced RAGE expression, and suppression of macrophage inflammatory responses." (PMID 26807573, 2016). "We obtained similar results, in that hyperglycemia enhanced RAGE and CD36 expression and decreased ABCA1 and ABCG1 expression." (PMID 26807573, 2016). "In the setting of hyperglycemia, AGE formation is prevalent compromising both the expressions of ABCA-1 and ABCG-1." (PMID 21957962, 2011).